NOTCH1 (notch receptor 1)
Diseases named in the same sentence as NOTCH1 in open-access papers (continued):
Sharing a sentence is not in itself a finding about the gene and the disease.
glioma (continued). "Thus, it is logical to suppose that glioma cells resistant to TMZ and protect themselves partly through the activity of Notch1 pathway, while GANT61 somehow abrogated this upregulation, reducing the chemoresistance and at last sensitizing glioma cells to TMZ." (PMID 27894350, 2016). "Here, the authors show that Notch1 activation in glioma stem cells induces expression of the lncRNA TUG1, which promotes self-renewal through the repression of differentiation genes, and that targeting TUG1 represses glioma growth in vivo." (PMID 27922002, 2016). "Notch1 and GFAP were considered to be markers of differentiated glioma cells." (PMID 26563263, 2015). "In contrast, Cheung and colleagues reported the absence of Notch1 in grade IV gliomas, raising the possibility that it may act as a tumour suppressor in different types of tumours." (PMID 40100070, 2025). "Consistent with this, PDGF‐D knockdown or overexpression in glioma cells led to corresponding changes in the expression of NOTCH1 protein, and NOTCH1 activation using Dll4 reversed the suppressive effects of PDGF‐D knockdown on the migration and invasion of LN18 cells." (PMID 40530904, 2025). "Although studies have shown that NOTCH1 helps to induce EMT in both healthy and neoplastic cells, its role as a marker of the mesenchymal phenotype is still controversial, especially in gliomas, where NOTCH1 has not yet been elucidated regarding its role in EMT." (PMID 40679044, 2025). "This suggests that NOTCH1 could act as a key integrator of stemness, proliferation, and invasive behaviors in GSC-CC cells, coordinating molecular programs that are spatially restricted to white matter-infiltrating glioma populations." (PMID 41375052, 2025). "Therefore, we suggested that Notch1 may mediate glioma TMZ resistance, and T+A@Glu‐NPs can downregulate Notch1 by degrading BRD4 protein, thereby reversing glioma TMZ resistance." (PMID 39544152, 2024). "The results of this study indicated that CSC exosomes function as information carriers, mediated the dedifferentiation of non-GSC glioma cells into GSCs by delivering Notch1 protein via Notch1 signaling activation, and increased the stemness and tumorigenicity of non-GSC glioma cells." (PMID 37887005, 2023). "While the mRNA levels of genes related to pluripotency (SOX2, KLF4, MYC and NOTCH1) were not obviously correlated with the clinical glioma grade or outcome, the mRNA level of POU5F1, which also plays a crucial role in PGC specification, was often linked to a higher glioma grade and poor outcome." (PMID 36435765, 2022). "In glioma, miR-34a suppresses cell cycle progression and proliferation of glioma cells through direct inhibition of the expression of MET receptor tyrosine kinases (c-MET RTK), Notch-1, Notch-2, cyclin-dependent kinase 6 (CDK6), cyclin 1 (CCND1), and silent information regulator 1 (SIRT1)." (PMID 35922753, 2022). "Therefore, Notch1 can promote EMT and the proliferation, migration, and invasion of gliomas." (PMID 36180477, 2022). "In addition to evaluating E-cadherin, the biomarker for the process of EMT, we also evaluated Notch1 and the wnt signaling because Notch1 as well as β-catenin are intricately connected to induction of EMT in various cancers, including gliomas." (PMID 34485294, 2021). "However, the biological behavior and related molecular mechanism of Notch1 in glioma initiating cells are not well reported worldwide." (PMID 31382985, 2019). "As a corollary, we have demonstrated a model where NKAP positively regulates the expression of Notch1, which results in an increasing secretion of M-CSF of SDF-1 in glioma cells, reinforcing significant bidirectional cross-talks between macrophages and glioma cells." (PMID 31277684, 2019).
glioma (continued). "Furthermore, down-regulation of NOTCH1 and its ligand DLL1 has been reported to inhibit tumor proliferation in glioma cell lines, which may play the function of promoting tumor proliferation." (PMID 31118022, 2019). "Therefore, in this work, since the Notch-1 and OPN molecules are related to the maintenance of angiogenesis and GSLCs, we analyze the distribution of Notch-1 and OPN immunopositivity in relation to nestin and CD133 and the proangiogenic factor VEGF in early to advanced stages of ENU-gliomas." (PMID 30140373, 2018). "Inhibition of Notch-1 led to delayed tumor growth and longer survival; it not only protected cardiomyocytes from ethanol-induced autophagy but also mediated oroxylin A-induced autophagic cell death in glioma cells." (PMID 26824182, 2016). "In addition, GSC exosomes serve as information carriers, facilitating the dedifferentiation of non-GSC glioma cells into GSCs by conveying Notch1 protein and activating Notch1 signaling, maintaining the dynamic equilibrium state of GSCs in the tumor microenvironment." (PMID 34722277, 2021). "Therefore, first, we tested whether or not the inactivation of Notch1 results in deceased glioma cell proliferation." (PMID 33381038, 2020). "As an information carrier, glioblastoma stem cells (GSC) EVs mediated the dedifferentiation of non-GSC glioma cells into GSCs by activating Notch1 signal to transmit Notch1 protein, thus enhancing the stemness and tumorigenesis of non-GSC glioma cells." (PMID 33670924, 2021). "It is interesting to note that we ruled out a reciprocal relationship between Notch1 and SNHG6, at least in our glioma cell line models." (PMID 34485294, 2021). "All in all, this data further support the importance of NOTCH1 as a regulator of TM network connectivity, but also suggests NOTCH1 as a principal regulator of oligodendroglioma growth, without specifically affecting PVN biology in this glioma subgroup." (PMID 33579922, 2021). "Considering both TRPM7 and Notch signaling function as oncogenes in glioma formation, it is not surprising to see that U87MG cells, transfected with M7-wt, express increased levels of Notch1 NICD, Notch2 NICD, and Notch3 NICD." (PMID 33381038, 2020). "We found that Notch1 and Hes1 were significantly upregulated in TMZ-treated glioma cells, but not in the combination of TMZ and GANT61-treated glioma cells." (PMID 27894350, 2016). "This analysis revealed no major changes in NOTCH1, NOTCH2 and NOTCH4 transcript levels in our glioma population." (PMID 24143218, 2013). "GSC could deliver SEVs to nonGSC glioma cells and increase Notch1 expression, which in turn mediated the dedifferentiation of nonGSC glioma cells into GSC and enhanced the stemness and tumorigenicity of nonGSC glioma cells." (PMID 35999601, 2022). "ELTD1 has emerged as an angiogenic biomarker, co-regulated with other angiogenic factors, such as VEGF, NOTCH1, and DLL4.113,114ELTD1 is transcriptionally upregulated in blood vessels of high-grade glioma tumors compared to vessels from low-grade gliomas and from nonmalignant control tissue." (PMID 33959717, 2021). "In addition, in the treatment with full-length Notch1 without the corresponding 3′-UTR and followed by miR-139-5p mimics for 48 h, we found that miR-139-5p partially inhibits forced Notch1 expression in glioma cells." (PMID 30170559, 2018).
glioma (continued). "The Notch1 signaling pathway was activated in GSCs; Notch1 protein was highly enriched in GSC exosomes; Notch1 signaling pathway and stemness-related protein expressions were increased in GSC exosome-treated, non-GSC glioma cells and tumor tissues generated by these cells." (PMID 37887005, 2023). "Moreover, GSC exosomes increased Notch-1, as well as stemness-related proteins such as CD133, nestin, octamer-binding transcription factor 4 (Oct4), and SRY-box transcription factor 2 (Sox2), in treated non-CSC glioma cells." (PMID 34638913, 2021). "Also, another study reported that GSCs produced exosomes carrying Notch1 protein; when these exosomes were absorbed into non-GSC glioma cells, Notch1 transferred from GSC exosomes activated the Notch1 signaling pathway, increasing the stemness and tumorigenicity of these non-GSC glioma cells." (PMID 34722277, 2021).
leukemia (209 papers, 2005 to 2026). A malignant (clonal) hematologic disorder, involving hematopoietic stem cells and characterized by the presence of primitive or atypical myeloid or lymphoid cells in the bone marrow and the blood. "To further immunophenotypically define these preLSCs, we assessed the expression of hematopoiesis-regulating receptors, such as Il-7r, Notch1, Kit, and Flt3, which have been implicated in leukemia development." (PMID 39849166, 2025). "T-ALL patients carrying NOTCH1 mutations show increased NICD levels in primary leukemia cells as well as increased mRNA expression of NOTCH1 targets such as HES1." (PMID 40441890, 2025). "For example, in leukemia cells caused by an abnormality in NOTCH1, NOTCH1 is generally bound to the genome, but only 10% of NOTCH binding sites respond to upstream signaling, and the majority of these 10% binding sites reside in SEs." (PMID 40672386, 2025). "As 43% of the CIMP cases also exhibit such activating mutations, targeting NOTCH1 can be an attractive therapeutic avenue for these leukemias." (PMID 38972954, 2024). "Following this framework, we successfully matched a specific CBD-rich Cannabis extract to T-ALL leukemia cells that harbor a NOTCH1 mutation." (PMID 39258755, 2024). "We have previously shown a specific CBD-rich Cannabis extract selectively induces apoptosis in T-ALL leukemia cell lines that harbor a NOTCH1 mutation." (PMID 39258755, 2024). "In the current study, we identified three unique phytocannabinoids that together selectively induce apoptosis in Notch1-mutated leukemia cells: CBD, CBDV, and the novel phytocannabinoid 331-18A." (PMID 39258755, 2024). "Aberrant Notch1 activity is associated with many other leukemia types and other cancers, including prostate, lung, ovarian, and renal." (PMID 39258755, 2024). "Supporting the oncogenic role of the N-Me region, leukemia development is impaired in mice transplanted with N-Me-deficient BM progenitors transduced with an oncogenic NOTCH1 allele (ΔE-NOTCH1)." (PMID 36674902, 2023). "Using a CRISPR/Cas9 MLL-AF4/-AF9 translocation model, the newly developed NOTCH1 inhibitor CAD204520 with less toxic side effects allowed us to unravel the impact of NOTCH1 as a pathogenic driver and potential therapeutic target in MLLr leukemia." (PMID 37833915, 2023). "Among them, SERCA (sarco/endoplasmic reticulum calcium ATPase) inhibitors have been identified as potential regulators of leukemia-associated NOTCH1 mutant signaling and cell cycle progression and expansion of T-ALL xenografts." (PMID 36674902, 2023). "More importantly, even when NOTCH1 participates secondarily, NOTCH1 activation is an early hallmark of T-cell leukemogenesis and a key regulator of the leukemia-initiating cell (LIC) activity of T-ALL." (PMID 36674902, 2023). "E2a-/- leukemias have mutations in the Notch1 gene and they are dependent on Notch signaling for their survival." (PMID 35371057, 2022). "The crosstalk between Notch1 and miR-19 is supported by the correlation between the high number of activating mutations in the Notch1 gene in more than 50% of leukaemia patients, and the high level of miR-19 in the same patients in T-ALL." (PMID 35055013, 2022). "E2a-/- leukemias are characterized by recurrent mutations in the Notch1 PEST domain and altered Notch1 splicing and transcription initiation leading to ligand independence." (PMID 35371057, 2022). "Our previous work showed that loss of the pioneer factor KLF4 in a NOTCH1-induced T-ALL mouse model accelerated the development of leukemia through expansion of leukemia-initiating cells and activation of the MAP2K7 pathway." (PMID 34504651, 2021). "In T-ALL, NOTCH1 is a driving oncogene, whose gain-of-function mutations induce the development of pre-T-cells to leukemia." (PMID 34440292, 2021).
leukemia (continued). "A recent study showed that VAV1 acts as a tumor suppressor in leukemia by promoting the degradation of ICN1 (intracellular domain of Notch1), while VAV1 mutation facilitates the malignant transformation of T cells." (PMID 34335756, 2021). "This approach enhanced the therapeutic window of thapsigargin as a NOTCH1 inhibitor and provided dual selectivity: leukemia over the normal cell and NOTCH1 mutated over wild-type receptors." (PMID 33407740, 2021). "In T-ALL, NOTCH1 is a driving oncogene, and the dominant active mutations induce the development of pre-T cells to leukemia." (PMID 33292596, 2020). "Aberrant NOTCH1 signaling is implicated in the progression of various cancer types including breast cancer, leukemias, HNSCC and squamous cancers of the skin, esophagus, cervix, and lung." (PMID 33322834, 2020). "Folate-derived Tg delivery strategy is an interesting approach to enhance the therapeutic window of Tg, providing dual selectivity: leukemia over normal cells and NOTCH1 mutated over wild-type receptors." (PMID 33374919, 2020). "NOTCH1 suppression causes cell cycle arrest and inhibition of leukemia growth in vitro in T-ALL xenografts and in a Drosophila intestinal stem cell model." (PMID 33003595, 2020). "Certain leukemias arise with inactivating FBXW7 mutations in the cancer cells that complement NOTCH1 activation by preventing ICN1 degradation." (PMID 33322834, 2020). "NOTCH1 plays an important role both in T-cell development and leukemia progression, and more than 60% of human T-ALLs harbor mutations in components of the NOTCH1 signaling pathway, leading to deregulated cell growth and contributing to cell transformation." (PMID 32708470, 2020). "JQ-FT is a NOTCH1 inhibitor with a dual selectivity, targeting both NOTCH1 mutations and leukemia cells." (PMID 33292596, 2020). "At relapse, this leukemia acquired a de novo PtenH123R mutation and also showed markedly decreased Notch1 mutant allele frequency." (PMID 31199785, 2019). "Taking advantage of the spectrum of Notch1 mutations observed in the thymus-transplantation model, we tested the anti-tumor activity of therapeutic mAb against leukemias characterized by Notch1 5′ deletions, HD- and PEST-domain mutations." (PMID 31399482, 2019). "New gene products that enhance signaling of leukemia-associated Notch1 mutants have been also identified." (PMID 31346528, 2019). "WES identified all 14 known Notch1 mutations, and also uncovered somatic mutations in the Notch pathway genes Notch4 and Cntn1 in two additional leukemias." (PMID 31199785, 2019). "As in relapsed human leukemias, these resistant murine T-ALLs were derived from pre-existing ancestral clones and they frequently showed loss of activated Notch1 expression and PI3K pathway activation." (PMID 31199785, 2019). "Recently, an elegant study found that conditional postnatal knockdown of Pten (shPten) in the hematopoietic compartment produced a highly disseminated T-ALL with the majority of leukemias harboring activating mutations in the Notch1 PEST domain." (PMID 29666622, 2018). "T-cell acute lymphoblastic leukemia (T-ALL) is a highly aggressive leukemia that is primarily caused by aberrant activation of the NOTCH1 signaling pathway." (PMID 30370059, 2018). "In this sample, the activating mutation found in NOTCH1 at diagnosis was lost, but two new NOTCH1 mutations were acquired together with a loss of function mutation in FBXW7, suggesting that the leukemia was “addicted” to activated NOTCH1 signaling." (PMID 29312904, 2017). "MiR-128-3p directly inhibits the expression of the tumor suppressor PHF6 and overexpression caused accelerated leukemia onset in the NOTCH1-sensitized mouse model." (PMID 28270163, 2017).